NECTIN4 (nectin cell adhesion molecule 4)
Diseases named in the same sentence as NECTIN4 in open-access papers (continued):
Sharing a sentence is not in itself a finding about the gene and the disease.
tumor (continued). "Box plot analysis revealed that Nectin-4 expression increased with tumor progression from normal epithelium to EC tissues, with almost no detection in nonadjacent normal tissue." (PMID 37345201, 2023). "The standardization of the method of detecting nectin-4 expression, the assessment of heterogeneity of expression within the tumor, and secondary lesions are just a few of them." (PMID 37958883, 2023). "Using agents targeting a very common ligand, such as Nectin-4, seems an effective strategy to treat mUC, as the tumor tissue highly expresses this target." (PMID 37781180, 2023). "Since treatments based on nectin-4 expression in some tumors are being launched, there is considerable potential to develop new therapies for neoplasms like HCC or CRC in the near future." (PMID 37568798, 2023). "In the study cited, BT7480 showed complete regression of nectin-4-positive tumor xenografts models with resistance to tumor relapse." (PMID 37568798, 2023). "TROP-2 and nectin-4 were initially added as the tumor targets for sacituzumab govitecan and enfortumab vedotin, meanwhile, it extended further to include HER2 as target for trastuzumab deruxtecan for better therapeutic index." (PMID 37671162, 2023). "Recently, nectin-4 has been identified as a tumor marker in several types of carcinoma, including lung, breast, ovarian, esophageal, gastric, pancreatic, liver, colon, and bladder cancers, and has been suggested to promote carcinogenesis." (PMID 38288120, 2023). "Tumor expression of targeted proteins, such as Nectin-4, is vital for ensuring antitumor responses to antibody–drug conjugates, such as EV." (PMID 37174031, 2023). "High expression of nectin-4 correlated significantly with tumor size, the presence of metastasis vascular invasion, and TNM stage." (PMID 37568798, 2023). "Nectin-4 was upregulated in tumors and correlated with disease stage (and N stage), tumor size and histological type." (PMID 37568798, 2023). "Compelling evidence has emerged in recent years supporting a new tumor biomarker, Nectin-4, in several different carcinomas." (PMID 37345201, 2023). "Efficiency was found to be dependent on both the dose and the nectin-4 tumor expression level in the anti-nectin 4 ADC and (N41mab-vcMMAE) was developed." (PMID 36294342, 2022). "Drug resistance, distant metastasis, tumor relapse, and poor prognosis are also related to the Nectin-4 overexpression." (PMID 35614462, 2022). "Single-cell analysis revealed that NECTIN family members, especially NECTIN4, are tumor-specific, uncovering a potentially targetable interaction with TIGIT in Tregs and exhausted T cells." (PMID 35995947, 2022). "In order to explore the anti-tumor effect of Nectin4 mCAR-T therapy in vivo, C57BL/6 mice were subcutaneously inoculated with hNectin4-Luc." (PMID 36479116, 2022). "The relationships between Nectin‐4 expression and signalling, tumour volume, tumour weight, and prognosis were analyzed in 34 CPLA patients." (PMID 35905293, 2022). "A close connection between Nectin-4 up-regulation and tumor metastases was confirmed in the GSE21257." (PMID 35953862, 2022). "Especially, BT7480, a novel, first-in-class, Nectin-4/CD137 Bicycle tumor-targeted immune cell agonistTM (Bicycle TICATM) was recently developed." (PMID 36348391, 2022). "As described in the literature, a partly cytoplasmic, partly membranous staining for Nectin-4 was observed in tumor cells." (PMID 36139571, 2022). "Nectin cell adhesion molecule 4 (NECTIN4) is highly expressed in malignant tumors and promotes tumor progression." (PMID 35256687, 2022). "Taken together, our present study firstly demonstrated the clear evidence that Nectin-4 is specifically up-regulated in OS tissues and cells, and its expression is closely related to tumor stage and metastasis." (PMID 35953862, 2022). "This suggests that AREG has limited value as a tumor marker, so we restricted our subsequent studies to Nectin-4 and HB-EGF." (PMID 36497350, 2022).
tumor (continued). "Enfortumab vedotin is an ADC targeting nectin-4, a surface molecule involved in cellular adhesion, expressed by tumor cells, mUC included." (PMID 35203620, 2022). "The expression of PD-1/PD-L1 (tumor cells, tumor-resident T-cells and macrophages) and nectin-4 were measured to complete the table." (PMID 35308243, 2022). "All-in-all, anti-Nectin-4 antibody was shown to be a theranostic carrier, providing an open platform for tumor visualization, screening, and treatment guidance." (PMID 35614462, 2022). "Firstly, immunohistochemistry (IHC) analysis was performed to examine the cellular expression of Nectin4 in a variety of tumor biopsies." (PMID 36479116, 2022). "An antibody-drug conjugate (enfortumab-vedotin) directed against nectin-4 has shown marked tumor remission rates in this tumor type, which is known for high expression rates of nectin-4." (PMID 36268557, 2022). "It has been reported to be a tumour marker and prognostic factor, and oncolytic virotherapy is being investigated using nectin‐4 as a therapeutic target." (PMID 35905293, 2022). "NECTIN4 expression in tumor cells was compared with that in normal human endothelial cells (i.e. human umbilical vein endothelial cells [HUVEC], human dermal microvascular endothelial cells [HDMEC], and human dermal blood endothelial cells [HDBEC])." (PMID 35256687, 2022). "Despite the histological difference between pure UC and non-urothelial variants such as SCC and ADENO, we report high expression level of Nectin-4 in those rare tumor subtypes." (PMID 36139571, 2022). "Nectin 1 ~ 3 is commonly enriched in normal adult tissues, while Nectin-4 was found to be specifically up-regulated in various tumors, having a significant role in tumor occurrence and development." (PMID 35953862, 2022). "Nectin-4 displayed a higher expression in OS tumor tissues compared with normal tissues, and its overexpression was positively associated with tumor stage and metastasis in OS patients." (PMID 35953862, 2022). "NECTIN1 and NECTIN4 are most strongly expressed in tumor cells, but NECTIN2 and NECTIN3 are also expressed in some lymphocyte cell types, while TIGIT is largely expressed in Tregs and exhausted CD4+ T cells." (PMID 35995947, 2022). "Nectin-4 can be utilized for new target-specific probes to improve tumor visualization and metastases detection in single-photon emission computerized tomography (SPECT)." (PMID 36553083, 2022). "Nectin-4 was found to have a predominant role in promotion of tumor-induced lymphangiogenesis by increasing lymphatic vessel density (LVD) and activating the chemokine axis (CXCR4/CXCL12)." (PMID 36553083, 2022). "Nectin-4 is specifically up-regulated in various tumors, exert crucial effects on tumor occurrence and development." (PMID 35953862, 2022). "Nectin-4 contributes to tumor proliferation, lymphangiogenesis and angiogenesis in malignant tumors and is an emerging target in tumor therapy." (PMID 36136143, 2022). "Collectively, these results confirmed that 99mTc-HYNIC-mAbNectin-4 can bind to Nectin-4-positive tumors in vivo with an excellent detection capability, high specificity, and good tumor retention." (PMID 35614462, 2022). "Further in vitro analyses revealed the involvement of NECTIN4 in the regulation of tumor cell proliferation, apoptosis, and angiogenesis." (PMID 35256687, 2022). "Nectin-4 appears to increase with tumor grade (e.g., based on the tumor-nodes-metastasis classification)." (PMID 36553083, 2022). "Nectin-4 plays a crucial role in tumor cell aggregation, migration and tumor progression because it can lead to the formation of cancer spheroids by increasing cell adhesion." (PMID 36497350, 2022). "Regarding nectin‐4 and the promotion of tumour growth, a mechanism that activates cell motility has been reported." (PMID 35905293, 2022). "Flow cytometric analysis showed that high-level expression of Nectin4 was present on the surface of various tumor cell lines." (PMID 36479116, 2022).
tumor (continued). "Even so, numerous studies reported that up-regulation of Nectin-4 was correlated with the tumor progression and worse prognosis in various cancers." (PMID 35953862, 2022). "In the EV-101 study almost all UC tumor biopsies had a high Nectin-4 expression, so that Nectin-4 expression was removed as a requirement for study inclusion." (PMID 34206980, 2021). "NECTIN4 also plays a role in tumor progression by modifying cell proliferation, apoptosis, metastasis, and angiogenesis." (PMID 33808400, 2021). "TIGIT has been investigated in tumor immunology and antibody-drug conjugate (ADC) targeting NECTIN4 also showed provisional anti-tumor efficacy in preclinical studies." (PMID 34611125, 2021). "Emerging targeted therapies (anti-FGFR and Nectin-4) are likely to change this paradigm, since treatment resistance will require the tumor to alter or lose the target." (PMID 33420073, 2021). "Sacituzumab govitecan and enfortumab vedotin firstly included Trop-2 and nectin-4 in the landscape of druggable tumor targets." (PMID 33509252, 2021). "Nectin-4 is moderately expressed in human skin and strongly expressed in tumor tissues, with an expression of >60% in UC." (PMID 34206980, 2021). "Promising results have been found for the combination of pembrolizumab with an antibody–drug conjugate (enfortumab vedotin) targeting tumor-expressed nectin-4 with an antibody to release the antimicrotubule agent auristatin-E for tumor cell destruction." (PMID 34885126, 2021). "In this group (n = 50), strong Nectin-4 expression was found to be an independent predictor of tumor progression." (PMID 32751328, 2020). "A larger phase II EV-202 trial (NCT04225117) is currently recruiting and estimates to enrol 240 patients and perhaps they will determine patient responses based on Nectin-4 tumor expression." (PMID 33019653, 2020). "Subsequent protein expression analyses revealed positive Nectin 4 expression in about 53% of late stage HGSOC tissues but impact on survival was only seen in those 13% of cases with >50% of positive tumor cells." (PMID 31137558, 2019). "Then the cellular studies in vitro and the nude mice tumor model in vivo were used to examine the regulatory role of Nectin-4 in the progression of EC." (PMID 31043861, 2019). "In order to study the effect of abnormal Nectin-4 expression on the regulation of tumor growth in vivo, we then established the subcutaneous transplantation mouse model." (PMID 31043861, 2019). "Of note, it has been revealed that over-expression of Nectin-4 in cancer progression can promote the intra-tumoral angiogenesis and facilitate the tumor growth." (PMID 31043861, 2019). "Several clinical investigations have revealed that Nectin-4 can serve as a tumor biomarker, and its over-expression in cancer tissues is significantly associated with cancer progression and poorer prognosis of the patients." (PMID 31043861, 2019). "The increasing anti-tumour activity of MV-Edm in human adenocarcinoma cells with up-regulated levels of nectin-4 suggested that its expression is correlated with MV-mediated oncolysis." (PMID 27782084, 2016). "In tumor cells, Nectin-4 is over-expressed on the cell surface and can be shed into the sera of patients." (PMID 27657109, 2016). "This raises the possibility that rMV-SLAMblind is even effective in some tumours that express nectin-4 intermittently." (PMID 27090874, 2016). "Nectin-4 is highly expressed in embryos and has been shown to be a tumor cell marker for breast, lung, and ovarian carcinomas." (PMID 27657109, 2016). "Nectin 4 can be considered as a tumor cell marker for breast, lung, and ovarian cancers, suggesting that it can be partially responsible for the selectivity of MV toward cancer cells." (PMID 26640815, 2015). "Our results revealed that diffuse nectin-3 expression was associated with a good prognosis, a higher score for nectin-2 was related to a poorer histological grade and a higher score for nectin-4 was related to a larger tumor size." (PMID 25690753, 2015).
tumor (continued). "Nectin 4 can be considered as a tumor cell marker for breast, lung, and ovarian cancers, suggesting that it can be partially responsible for the selectivity of measles virus toward cancer cells." (PMID 26640816, 2015). "It has been demonstrated recently that nectin-4 is necessary for the tumor selectivity of infection by MV in some breast cancers." (PMID 24832799, 2013). "Of these, only the human tumor cell marker PVRL4 (Nectin 4) rendered cells amenable to measles virus infections." (PMID 21901103, 2011). "To extend this study, we analyzed the expression of Nectin-4 in a panel of primary cells and tumor cells from different origins using two monoclonal antibodies (mAbs) (N4.40 and N4.61) and FACS analysis." (PMID 17474988, 2007). "Relevant Nectin‐4 expression in tumour samples was observed in only two of the six patients." (PMID 40847665, 2026). "In this study, we investigated whether Nectin-4 PET imaging could provide a quantitative assessment of changes in accessible Nectin-4 over time and track TE at the tumor in response to varying doses of EV." (PMID 41499516, 2026). "Nectin-4 was exclusively expressed by tumor cells and correlated with low immune infiltration." (PMID 41364531, 2025). "Decreased surface expression of nectin-4 of tumor cells may predict resistance to EV in the metastatic setting." (PMID 40828887, 2025). "However, we found significantly higher Nectin‐4 expression in the matched positive LNs compared to the primary tumours (median H‐score 100 vs 40)." (PMID 39801278, 2025). "Although further validation is necessary for generalization, these examples suggest that loss of TAAs, such as NECTIN4 and CLDN18.2, might occur in metastatic lesions owing to adaptation or plasticity of tumor cells in their metastatic niche." (PMID 41164107, 2025). "Also, a role for nectin-4 has been demonstrated in promoting tumor-induced lymphangiogenesis and lymphatic metastasis in part through modulating the CXCR4/CXCL12-LYVE-1-axis." (PMID 40507273, 2025). "Based on the association shown between Nectin‐4 expression and EV sensitivity, these results indicate that some subgroups (SARC, Sc/NE) may achieve lower anti‐tumour activity when treated with EV." (PMID 39801278, 2025). "Thirty percent of tumours (41/136) with pure NOS histology exhibited high Nectin‐4 expression." (PMID 39801278, 2025). "Our findings demonstrated a significantly stronger expression of Nectin-4 in LSCC, prompting further investigation into whether variations in Nectin-4 expression influence tumor differentiation." (PMID 40699695, 2025). "This observed shift from membranous to cytoplasmic localization of Nectin-4 in tumor cells may reflect its involvement in the process of laryngeal carcinogenesis and may represent the basis for further important research in this context." (PMID 40699695, 2025). "Both Nectin-2 and Nectin-4 expressions were more pronounced at the invasive tumor margins." (PMID 40699695, 2025). "Indeed, Nectin-4 was identified in a screen for genes required for anchorage-independent viability, a process that is crucial for the survival of tumor cells in the ascites microenvironment." (PMID 40075748, 2025). "Our results revealed a low spatial heterogeneity of Nectin‐4 expression within the primary tumour." (PMID 39801278, 2025). "Because EV binds selectively to nectin-4, EV intuitively may bind tumor cell surfaces that overexpress nectin-4 more effectively compared to cell surfaces that underexpress or do not express nectin-4." (PMID 40225697, 2025). "Western blotting and flow cytometry showed that HCE-T cells express Nectin-4; thus, anti-Nectin4-VcMMAE may kill corneal epithelial cells via on-target-off tumor mechanisms." (PMID 40507807, 2025). "Our results demonstrate significantly higher and more heterogenous Nectin-4 expression, especially in the cytoplasm of the tumor samples, and indicate that Nectin-4 may serve as a diagnostic, prognostic, and therapeutic biomarker in LSCC." (PMID 40699695, 2025).